C6orf62 (chromosome 6 open reading frame 62)
Synonyms: XTP12; Nbla00237; FLJ12619; DKFZP564G182; dJ30M3.2
Tractability: PROTAC: ubiquitination databases record sites on it.
Gene: Protein-coding gene on chromosome 6 (24,704,856 to 24,720,874, reverse strand). Ensembl gene ENSG00000112308.
Subcellular location (Human Protein Atlas): Cytosol
Genetic constraint (gnomAD): Loss-of-function variants: 11 observed, 23.76 expected, observed/expected ratio (o/e) 0.46, 90% interval 0.29 to 0.77. The upper end of that interval is the gene's LOEUF score, 0.77, which puts it in group 3 of 6, group 1 being the genes least tolerant of losing a copy. Missense variants: 164 observed, 244.44 expected, observed/expected ratio (o/e) 0.67, 90% interval 0.59 to 0.76. Synonymous variants: 106 observed, 86.3 expected, observed/expected ratio (o/e) 1.23, 90% interval 1.05 to 1.44.
Homologues: Orthologues: chimpanzee C6H6orf62 (100% identical), macaque C4H6orf62 (100% identical), mouse BC005537 (100% identical), guinea pig C6orf62 (99% identical), rat C17h6orf62 (99% identical), dog C6orf62 (99% identical), pig C6orf62 (99% identical), tropical clawed frog c6h6orf62 (93% identical), zebrafish C19H6orf62 (87% identical).
Diseases named in the same sentence as C6orf62 in open-access papers:
C6orf62 is named in the same sentence as 2 diseases in open-access papers, as found by Europe PMC text mining. Sharing a sentence is not in itself a finding about the gene and the disease. The quoted sentences say what the papers report.
tumor (1 paper, 2019). "Additional genes that had similar DNA and RNA frequency as DUSP5 and EI24 but no previous research on their potential role as a tumor suppressor were UBXN11, CAPN15, C6orf62, GPRIN1, KIAA2018, PCDHGA10, and PCGF1." (PMID 31484939, 2019).
C6orf62 also shares sentences with these, for which no sentence is quoted: prostate adenocarcinoma (1 paper).